KRAS (KRas proto-oncogene, GTPase)
Diseases named in the same sentence as KRAS in open-access papers (continued):
Sharing a sentence is not in itself a finding about the gene and the disease.
gastric adenocarcinoma (17 papers, 2017 to 2025). "However, KRAS mutation may be relevant to GEN-FGML etiology with the same frequency as common-type gastric adenocarcinoma." (PMID 34268625, 2021). "According to the cBioPortal website, KRAS and APC variants occur in 15% and 12% of stomach adenocarcinoma, respectively." (PMID 40916582, 2025). "KRAS WT amplifications were confirmed in esophageal adenocarcinoma (∼15.5%), adenocarcinoma of the gastroesophageal junction (∼10.2%), stomach adenocarcinoma (∼4.6%), and esophageal SCC (∼4%)." (PMID 39711431, 2025). "Amplification of the KRAS locus and corresponding protein expression was analyzed in 582 gastric adenocarcinomas employing fluorescence in-situ hybridization (FISH) and immunohistochemistry." (PMID 32571252, 2020). "Nothing is known about the intratumoral heterogeneity of KRAS amplification in gastric adenocarcinomas and its importance and prognostic relevance in a large Caucasian patient population." (PMID 32571252, 2020). "Despite the heterogeneous distribution of KRAS amplified tumor clones, KRAS amplified gastric adenocarcinomas represent a therapeutically highly interesting tumor subgroup." (PMID 32571252, 2020). "Despite the heterogeneous distribution of KRAS amplified tumor clones, KRAS amplified locally advanced or metastasized gastric adenocarcinomas represent a therapeutically highly relevant tumor subgroup." (PMID 32571252, 2020). "Nothing is known about the possible intratumoral heterogeneity of KRAS amplified tumor cell clones in gastric adenocarcinoma." (PMID 32571252, 2020). "Gastric adenocarcinomas showed a varying homogeneity of KRAS amplified tumor clones within the tumor." (PMID 32571252, 2020). "The analysis of KRAS amplification in relation to the molecular classification of gastric adenocarcinoma (according to TCGA) revealed that 24 (88.8%) were related to tumors with chromosomal instability (CIN) and 3 (11.1%) were related to genomically stable (GS) tumors (p = 0.282)." (PMID 32571252, 2020). "For esophageal and gastric adenocarcinomas it has been reported that high-level amplifications of KRAS resulted in a relevant copy number increase of the wild-type KRAS gene in the absence of coding mutations." (PMID 32571252, 2020). "We demonstrate that co-activation of the KRAS and PIK3CA/PTEN signaling pathways is sufficient for the development of early-stage gastric adenocarcinomas." (PMID 39128004, 2024). "Little is known about the (prognostic) relevance and (heterogenic) distribution of KRAS amplification in gastric adenocarcinomas, especially in Non-Asian patients." (PMID 32571252, 2020).
cardiofaciocutaneous syndrome (16 papers, 2010 to 2025). "The remaining three individuals have a diagnosis of CFC syndrome with pathogenic variants in KRAS (n = 3)." (PMID 37774117, 2024). "High and narrow palate with submucous clefting is a typical craniofacial feature in cardiofaciocutaneous syndrome, which is caused by mutations in KRAS, BRAF, MAP2K1 and MAP2K2." (PMID 34897389, 2022). "Constitutive active mutations in more downstream genes such as KRAS and BRAF result in an increased activation of the MAPK/ERK pathway and hence in short stature syndromes as for example Noonan or cardio-facio-cutaneous syndrome." (PMID 23155469, 2012).
chronic myeloid leukemia (16 papers, 2013 to 2025). "Despite this, small-molecule inhibitors targeting SOS1 have shown limited efficacy in clinical trials for KRAS-mutant cancers, and their potential as a therapeutic approach for chronic myeloid leukemia (CML) remains largely unexplored." (PMID 39437162, 2025). "Among these genes, MTOR, STAT3, MCL1, LAMC1, and KRAS have been reported to play roles in imatinib resistance in chronic myeloid leukemia in parallel with our findings." (PMID 38916832, 2024). "In chronic myeloid leukemia cells, miR-155 regulates MAPKs through targeting KRAS or SOS, upstream signaling of MAPKs." (PMID 29137434, 2017). "Another attribute of some well-known oncogenes, such as BCR-ABL fusion in chronic myeloid leukemia or mutant EGFR or KRAS in LUAD, is the dependence on sustained expression of those oncogenes for the maintenance of cell growth or viability." (PMID 27776121, 2016). "The PROTAC SIAIS562055 sustainably degrades SOS1 and inhibits downstream ERK signaling, showing strong antiproliferative activity and synergistic effects with KRAS inhibitors in KRAS-mutant cancers and BCR–ABL inhibitors in chronic myeloid leukemia." (PMID 39437162, 2025). "Significance: The PROTAC SIAIS562055 sustainably degrades SOS1 and inhibits downstream ERK signaling, showing strong antiproliferative activity and synergistic effects with KRAS inhibitors in KRAS-mutant cancers and BCR–ABL inhibitors in chronic myeloid leukemia." (PMID 39437162, 2025).
endometrioid ovarian cancer (16 papers, 2008 to 2025). "Type I (5–10%) includes low-grade serous, mucinous, clear cell, and endometrioid ovarian carcinomas, are typically KRAS, PIK3CA, PTEN, or BRAF mutated, and diagnosed frequently at early stages." (PMID 31197119, 2019). "Moreover, mutations causing KRAS overactivity have been reported as markers of epithelial and endometrioid ovarian cancer." (PMID 34859047, 2021). "Molecular profiling of human endometrioid ovarian cancers revealed that the most prevalent mutations are similar to those observed in clear-cell ovarian cancer and include PIK3CA (40%), ARID1A (30%), KRAS (30%), PTEN (16%), and PPP2R1A (16%)." (PMID 32679669, 2020). "In accordance with these results, activation of oncogenic KRAS and PI3K pathways and inactivation of tumor suppressor genes PTEN and ARID1A are suggested pathogenic mechanisms for clear-cell and endometrioid ovarian cancers." (PMID 26413541, 2015). "Activation of oncogenic KRAS and PIK3CA pathways and inactivation of tumor suppressor genes, ARID1A and PTEN, are observed in clear cell and endometrioid ovarian carcinomas, respectively." (PMID 34454550, 2021).
follicular thyroid carcinoma (16 papers, 2011 to 2025). "NRAS, HRAS, and KRAS mutations, which are seen in 30–50% of follicular thyroid cancer (FTC), were detected in 8% of classic and in 33% of follicular variant PTCs." (PMID 34630336, 2021). "It has been shown that mutations in the RAS family genes (NRAS, KRAS, HRAS) are most commonly associated with follicular thyroid carcinoma (FTC), but they are also present in three other types, including anaplastic thyroid cancer (ATC)." (PMID 39767735, 2024). "Gene alterations in follicular thyroid carcinoma include point mutations in HRAS, NRAS, and KRAS genes." (PMID 36607876, 2023). "RAS alterations can occur in 12.7% (8.5% NRAS, 3.5% HRAS, and 0.7% KRAS) of the PTC cohort, 40-50% of follicular thyroid carcinoma (FTC), and 20-25% of follicular adenomas." (PMID 30915113, 2019). "Presumably, KRAS and concomitant PTEN deletion can induce malignant transformation in the aggressive form of follicular thyroid carcinoma." (PMID 27703585, 2016).
Hypertension (16 papers, 2010 to 2026). The presence of chronic increased pressure in the systemic arterial system. "We are not aware of any studies evaluating associations between KRAS mutational status and dyslipidemia in the NSCLC and CRC patients except that an NSCLC patient with dyslipidemia, hypertension, and the KRAS G12C mutation has been reported recently." (PMID 25158139, 2014). "KRAS mutation was associated with T stage as well as hypertension." (PMID 34368001, 2021). "This case report presents a 91-year-old patient with KRAS-mutant mCRC who also suffered from hypertension, making her ineligible for intensive treatment." (PMID 40224173, 2025). "These comparisons showed that older age at diagnosis, smoking, dyslipidemia, hypertension, and family cancer history were more frequent in NSCLC than in CRC patients when KRAS mutations were present (P ≤ 0.04)." (PMID 25158139, 2014). "These comparisons showed that the NSCLC patients had higher rates of older age at diagnosis, smoking, dyslipidemia, hypertension, and family cancer history than the CRC patients when KRAS mutations were present." (PMID 25158139, 2014). "The suitability of oxaliplatin rechallenge as third-line treatment in a patient with KRAS-mutated mCRC, who also presented with controlled hypertension and controlled type 2 diabetes (without neuropathy), was assessed." (PMID 34199694, 2021). "Neutropenia, thrombocytopenia, stomatitis, epistaxis, and hypertension occurred more frequently amongst patients treated with ramucirumab and FOLFIRI relative to placebo and FOLFIRI regardless of KRAS status or first-line TTP." (PMID 34298750, 2021).
juvenile myelomonocytic leukemia (16 papers, 2018 to 2025). A myelodysplastic/myeloproliferative neoplasm of childhood that is characterized by proliferation principally of the granulocytic and monocytic lineages. "Moreover, DCBLD1 interacts with KRAS, which is a key diagnostic and prognostic gene associated with various hematological tumors such as juvenile myelomonocytic leukemia." (PMID 38752789, 2024). "Herein, we report concurrent somatic KRAS mutation and germline chromosome 10q22.3-q23.2 deletion in a patient with juvenile myelomonocytic leukemia, developmental delay, and multiple congenital malformations, including distinct facial features, club feet, and cryptorchidism." (PMID 30012129, 2018). "Phenotypically related to pCMML, juvenile myelomonocytic leukemia (JMML) is a pediatric neoplasm often initiated by germline (CBL, NF1, PTPN11) or somatic (NRAS, KRAS, CBL, RRAS) RAS-activating mutations and is described as a bona fide RASopathy26,27." (PMID 34006870, 2021). "Juvenile myelomonocytic leukemia (JMML) is a rare pediatric MDS/MPN overlap syndrome that is characterized by somatic mutations in NF1, CBL, NRAS, KRAS or PTPN11 that result in the activation of RAS/MAPK or JAK/STAT signaling." (PMID 31171568, 2019). "In this regard, the results of a pairwise analysis study comparing patients with KRAS mutations showed 26 differentially expressed lncRNAs (17 upregulated and 9 downregulated) compared to juvenile myelomonocytic leukemia (JMML) patients without this mutation." (PMID 34489556, 2022). "This important role of the NLRP3 inflammasome in the pathogenesis of myeloid malignancies and the newly identified KRAS/RAC1/ROS/NLRP3/IL-1β axis has been demonstrated in chronic myelomonocytic leukemia (CMML), juvenile myelomonocytic leukemia (JNNL) and AML patients harboring the KRAS mutation." (PMID 33525345, 2021). "Supporting this, they found increased caspase-1 activation and IL-1β production in CMML, juvenile myelomonocytic leukemia (JMML) and AML patients with KRAS mutations as compared to patients without KRAS mutations." (PMID 35155452, 2021).
Pleural effusion (16 papers, 2016 to 2025). The presence of an excessive amount of fluid in the pleural cavity. "On the contrary, there was only one plasma liquid biopsy sample with a KRAS variant where the matching pleural effusion sample (both cfDNA and sediment) remained wild-type (case 7)." (PMID 34257581, 2021). "This manuscript reports a case of a patient with advanced NSCLC with pleural effusion and KRAS mutations treated poorly with conventional chemotherapy who had long‐term (more than 18 months) benefit with immunotherapy combined with an anti‐angiogenic inhibitor in Shanghai General Hospital." (PMID 40488279, 2025). "For case #34 (KRAS-G12D with 26.5% VAF), direct cytofluid pleural effusion (500 μL input) and DNA extracted from this effusion (40 μL input) were used to test the KRAS cartridge, and both resulted in KRAS positive mutation (G12D) with high Cq values of 28.9 and 30.8, respectively." (PMID 36293374, 2022). "Furthermore, an additional examination demonstrated an oncogenic KRAS mutation at codon 12 (p.G12D) in both palate tumor and in pleural effusion." (PMID 30634950, 2019). "Furthermore, presence or abscense of KRAS mutation in pleural effusion was examined." (PMID 30634950, 2019). "Although the literature on this subject is limited, tumor alterations, mainly in the EGFR and KRAS genes, have been detected in EV-derived DNA from biofluids such as plasma, pleural effusion, and cerebrospinal fluid." (PMID 39684756, 2024). "Pleural effusion was significantly less common among KRAS-positive patients, compared to EGFR-positive patients or ALK-positive patients (p = 0.046 and p = 0.026, respectively)." (PMID 27518729, 2016). "Pleural effusion was significantly less common among KRAS-positive patients, compared to EGFR-positive patients and ALK-positive patients (p = 0.046 and p = 0.026, respectively)." (PMID 27518729, 2016). "As next we evaluated our targeted EGFR, KRAS and BRAF test results from cfDNA obtained from pleural effusion and blood and from gDNA isolated from sediment cell blocks and lung biopsies." (PMID 34257581, 2021).
germ cell tumor (15 papers, 1991 to 2025). A benign or malignant, gonadal or extragonadal neoplasm that originates from germ cells. "KRAS mutations are present in germ cell tumors (12%) while STK11 are rare, found in less than 1% of mutations identified based on TCGA analysis." (PMID 40723253, 2025). "One mixed germ cell tumor case exhibited both a KRAS missense variant p.G12D and a copy number gain alteration for KRAS (TGCT-24)." (PMID 41009531, 2025). "KRAS amplification (median 11 copies, range 5-421) was rare across most tumor types but common in germ cell tumors (24%) and esophageal adenocarcinoma (18%)." (PMID 36494601, 2022). "Chromosomal gains of the 12p arm containing KRAS, a gene commonly found in testicular germ cell tumors, occur in up to 80% of patients with dysgerminoma." (PMID 32485873, 2020). "Four KRAS alterations were present in three mixed germ cell tumors (TGCT-10, TGCT-24, TGCT-25)." (PMID 41009531, 2025). "LP-WGS of the plasma sample at diagnosis prior to initiation of chemotherapy showed a highly complex pattern of whole chromosome and segmental gains and losses, including a gain of 12p and amplification of a region in 12q that included KRAS, alterations that are characteristic for germ cell tumor." (PMID 36805676, 2023). "KRAS, CDKN1B, CCND2, ETV6, and RAD52 mutations are the most common in germ cell tumors." (PMID 37958970, 2023). "A subset of germ-cell tumors in non-epithelial ovarian malignancies can develop KRAS-activating mutations, as well as other genetic changes such as KIT and MAPK." (PMID 36686734, 2022). "The most prevalent changes in germ cell tumors are CDKN1B Amplification, KRAS Amplification, CCND2 Amplification, ETV6 Amplification, and RAD52 Amplification." (PMID 37958970, 2023).
hyperplastic polyp (15 papers, 2005 to 2026). A polyp found mainly in the stomach and colon. "All serrated polyps (hyperplastic polyps or sessile serrated adenoma/polyps) were KRAS or BRAF-mutated, mostly the latter (70.6%, n = 12/17)." (PMID 32517177, 2020). "KRAS mutations have been reported in 40% of CRCs and contribute to the development of colorectal adenomas and hyperplastic polyps." (PMID 22997602, 2012). "Furthermore, they highlight a possible role for Abi1 as a marker for early KRAS mutation in hyperplastic polyps." (PMID 22808230, 2012). "Early KRAS mutations have been identified in left-sided hyperplastic polyps." (PMID 22997602, 2012). "We report a gastric foveolar‐type hyperplastic polyp of the duodenum harboring mutations in the GNAS and KRAS genes." (PMID 40964650, 2026). "Herein, we report a duodenal gastric foveolar‐type hyperplastic polyp with GNAS and KRAS mutations, highlighting the importance of histopathological and molecular evaluation even in lesions without cytological dysplasia." (PMID 40964650, 2026). "Based on these findings, the final diagnosis was a gastric foveolar‐type hyperplastic polyp harboring GNAS and KRAS mutations." (PMID 40964650, 2026). "Collectively, these findings support the diagnosis of a gastric foveolar‐type hyperplastic polyp of the duodenum harboring GNAS and KRAS mutations." (PMID 40964650, 2026). "We found 20 KRAS mutations and 24 BRAF mutations in these 65 hyperplastic polyps." (PMID 26910894, 2016). "Similarly, another study reported the finding of KRAS mutations in tissue specimens from patients with colitis, hyperplastic polyps, and normal colonic mucosa that did not have any kind of neoplasia." (PMID 28199989, 2017). "Based on the observations that polyps with mutations in the KRAS gene do not develop to cancer and that hyperplastic polyps do not carry a mutation in the APC gene, it seems reasonable to speculate that the first rate-limiting step in the development of CRC are mutations in the APC pathway." (PMID 30029640, 2018).